EGFR (epidermal growth factor receptor)
Diseases named in the same sentence as EGFR in open-access papers (continued):
Sharing a sentence is not in itself a finding about the gene and the disease.
lung cancer (continued). "We reason that inhibitors targeting FAK might interact with EGFR TKIs to prevent or delay the occurrence of acquired resistance and progression of lung cancer." (PMID 33287873, 2020). "Combinatorial treatment of retinoids with EGFR-TKIs drugs in EGFR-TKIs resistance lung cancer cells promotes the activation of GATA6 and then inhibits the activation of EGFR/Wnt signaling pathways and favors the association of RXR, RARβ, and cellular retinoic acid binding protein-2 (CRABP2)." (PMID 32293355, 2020). "TRIM27 expression is associated with poor prognosis of EGFR-mutated lung cancers, indicating that TRIM27 status may be related to anticancer therapy response in lung cancer with EGFR mutations." (PMID 33264103, 2020). "An in vitro experiment indicated that exosomes secreted by EGFR‐mutant non‐small cell lung cancer cell lines PC9 and HCC827 were more capable of promoting CD8 T cell apoptosis than EGFR wild‐type cell lines H1299 and SK‐MES‐1 (P = 0.007 and P = 0.010, respectively)." (PMID 32500560, 2020). "However, establishing the best combination regimen for EGFR wild type lung cancers with low PD-L1 expression remains daunting." (PMID 32899191, 2020). "THC and CBD inhibited the proliferation and expression of EGFR in the lung cancer cells studied." (PMID 32049991, 2020). "Indeed, TKIs used in lung cancer own anti-EGFR activity (gefitinib and erlotinib), while TKIs used in RCCs have mainly anti-vascular endothelial growth factor (VEGF) properties (sunitinib, sorafenib, axitinib and pazopanib)." (PMID 32325628, 2020). "However, there is no good cellular model to dissect the mechanism of resistance to TKIs in EGFR-C797S-mutant lung cancer." (PMID 33396393, 2020). "EGFR mutations often occur among adenocarcinoma lung cancer subtypes, females, never-smokers, and East Asians." (PMID 32977782, 2020). "This is especially the case for c.2369C>T p.(Thr790Met), as this variant has been reported to occur in less than 5% of treatment naïve primary lung cancers, but in 50% of treated NSCLC as a concomitant resistance variant in combination with another sensitizing EGFR variant." (PMID 32357863, 2020). "The alterations in EGFR can lead to constitutive activation of cell proliferation and contribute to prognosis which makes it a plausible target in specific tumors such as breast and lung cancer." (PMID 33202642, 2020). "Even though Osimertinib emerged as an advanced EGFR-TKI that could be used for treatment of lung cancer patients that had progressed on earlier generation EGFR-TKIs, it has emerged that Osimertinib resistance is also a clinical reality." (PMID 32641854, 2020). "Can an end-to-end deep learning network model be used to identify patients with stage IV epidermal growth factor receptor (EGFR) variant–positive non–small cell lung cancer who will not benefit from EGFR–tyrosine kinase inhibitor (TKI) therapy?" (PMID 33331920, 2020). "The development of acquired resistance to osimertinib (Osim) (AZD9291 or TAGRISSOTM), an FDA‐approved third‐generation epidermal growth factor receptor (EGFR) inhibitor for the treatment of EGFR‐mutant nonsmall cell lung cancer (NSCLC), limits the long‐term benefits for patients." (PMID 32003107, 2020). "Furthermore, the inhibition of oxidative phosphorylation has been shown to abrogate resistance to EGFR inhibitors in EGFR-driven lung cancers, docetaxel in prostate cancer, MAPK inhibitors in melanoma and 5-fluorouracil (5FU) in colon cancers." (PMID 32570870, 2020). "Perhaps the most significant result was that the PW laser reduced the viability of 93%±12% of the population of lung cancer cells when combined with anti-EGFR targeting S-Au40-849s (after 24 h incubation), in comparison to the CW which destroyed almost half (46%) of the cells." (PMID 32635387, 2020). "In addition, FASN inhibition showed cytotoxic effects in lung cancer and resensitized cells to chemotherapy, anti-EGFR and anti-HER2 therapies in breast cancer." (PMID 32438613, 2020).
lung cancer (continued). "Those includes EGFR c.2369C > T p.T790M, an important biomarker for patients with lung cancer." (PMID 32738923, 2020). "However, previous studies show activation of the EGFR pathway by FGFR4 in lung cancers and colon cancers." (PMID 33037736, 2020). "Exosomes extracted from lung cancer cell lines with and without EGFR mutation were used to test the function of promoting apoptosis in vitro." (PMID 32500560, 2020). "We hypothesize that sublethal radiation activates EGFR and HER2, which subsequently up-regulates MMP-9 and associates with lung cancer cell survival and invasiveness." (PMID 32143669, 2020). "In our study, pharmacological experiments indicated that LINC00152 might be a combination therapy target with EGFR for lung cancer." (PMID 32774169, 2020). "The discrepancy between studies might reflect the distinct biological feature of EGFR mutant lung cancer." (PMID 32693792, 2020). "Additionally, EGFR-mutant lung cancer cells display higher sensitivity to the PARP inhibitor olaparib." (PMID 32093123, 2020). "MET/EGFR signaling modulates cell proliferation in lung cancer." (PMID 31918742, 2020). "Thus, HB-EGF drives arsenic-induced carcinogenesis, tumor growth, and lung cancer development via the EGFR/PKM2/HIF-1α pathway." (PMID 32695675, 2020). "Since the clinical efficacy of TKIs is ultimately limited by the development of acquired resistance, further investigation of novel molecular mechanisms is essential to develop strategies to overcome or delay the acquired resistance to TKIs in EGFR-mutant lung cancer." (PMID 33014814, 2020). "Although it will be difficult to directly test whether chromosome 6 is the one present in those bridges, it is important to note that gain of chromosome 6 has already been observed in mouse models of Ras‐ or EGFR‐driven lung cancer." (PMID 32030896, 2020). "Similarly, the EGFR-blocking antibody cetuximab has been shown to induce autophagy in lung cancer cell lines, promoting cell survival." (PMID 33299639, 2020). "According to a previous study, the presence of mesenchymal–epidermal transition (MET) receptor amplification was analyzed as a second mechanism of gefitinib resistance; 20% of EGFR T790M-resistant patients among a number of lung cancer patients were observed to have increased MET receptor levels." (PMID 32133284, 2020). "Under the control of mutated epidermal growth factor receptor (EGFR), renin-angiotensin system (RAS), methionine (MET) or other tumorigenic pathways, vascular endothelial growth factor (VEGF) and other mediators are over-expressed in lung cancer patients." (PMID 33243184, 2020). "Moreover, in our study, EPS15 and the other lung cancer-specific EV markers, GPRC5 and TSG101, were associated with the “negative regulation of the epidermal growth factor receptor” signaling pathway." (PMID 32916986, 2020). "EGFR-TKI targeted therapy is one of the major treatment modalities in lung cancer." (PMID 32034239, 2020). "Additionally, the discovery of lung cancer driver genes and their targeted inhibitors, such as epidermal growth factor receptor (EGFR) and ALK receptor tyrosine kinase inhibitors, has achieved remarkable clinical benefits." (PMID 33159035, 2020). "A similar phenomenon has been described in lung cancer, whereby cells under oxidative stress are resistant to tyrosine kinase inhibitors, including erlotinib, due to abnormal EGFR activation and trafficking that results from its localization to ceramide-rich rafts." (PMID 32082486, 2020). "In order to determine whether parthenolide can inhibit the expression of EGFR in vitro, we observed the effect of parthenolide on EGFR signal pathway in EGFR mutant lung cancer cells." (PMID 33292235, 2020).
lung cancer (continued). "They further highlight the role tumor ECM composition could have in influencing EGFR dependent lung cancers." (PMID 32719793, 2020). "Non-small-cell lung cancer (NSCLC) consists of nearly 85% of lung cancer cases and targeted therapeutics based on driver mutations of NSCLC, such as mutations of epidermal growth factor receptor (EGFR) and anaplastic lymphoma kinase (ALK), have significantly prolonged the survival of patients." (PMID 32611363, 2020). "We propose that targeting Mig-6 may be a promising strategy to overcome the EGFR-TKI resistance in lung cancer." (PMID 32552717, 2020). "The gene mutations in lung cancer have different results among different countries, for example, the frequency of EGFR mutation of Asian female never‐smokers higher than female never‐smokers of the west countries." (PMID 32657049, 2020). "Changes in CEA expression patterns between inital diagnosis and disease progression may reflect oligoclonality of lung cancer cells with distinct chemoresistant and metastatic properties conferred by EGFR-TKI treatment." (PMID 32034239, 2020). "However, there are two big challenges against effective therapy--the secondary EGFR mutation-associated TKI resistance and brain metastasis (BMs) of lung cancer." (PMID 32483443, 2020). "In terms of potential mechanism, PKP2 could regulate the activity of Wnt/β-catenin in colon cancer-associated fibroblasts, and PKP2 promoted the proliferation and migration of lung cancer by activating EGFR signaling pathway." (PMID 33088217, 2020). "In patients with epidermal growth factor receptor (EGFR)-mutant non–small-cell lung cancer (NSCLC) with brain metastases, it remains controversial whether the use of EGFR-tyrosine kinase inhibitor (TKI) alone without radiotherapy (RT) is an optimal approach." (PMID 32298306, 2020). "Furthermore, the E3 ubiquitin ligase NEDD4 interacted with EGFR, which mediated lung cancer cell migration through activating CTSB." (PMID 32331211, 2020). "In this perspective, our result may provide an alternative method to non-invasively assess EGFR information of primary lung cancer and offers a great supplement to biopsy, thereby making a proper first-line treatment of lung cancer." (PMID 32483122, 2020). "nAChRs, β-AR, and EGFR often coexpress on human lung cancer cells and airway epithelial or endothelial cells that might lead to cancer progression." (PMID 31956359, 2020). "EGFR over-expression plays a key role in the development and progression of lung cancer." (PMID 33247670, 2020). "Overcoming alternative survival signaling pathways for activating the EGFR signaling network in lung cancer progression may lead to more effective therapeutic strategies." (PMID 33042262, 2020). "Activating the EGFR/FAK pathway promotes migration of A549 lung cancer cells." (PMID 32148496, 2020). "Similarly, our findings showed that As2O3 reduced BASP1 expression and induced synergistic effects to kill lung cancer cells when combined with EGFR TKIs." (PMID 33042262, 2020). "Our studies demonstrate that CuD overcomes gefitinib resistance by blocking EGF binding to induce EGFR-mediated signaling and cell death, which suggests that CuD treatment could be useful for treating gefitinib-resistant lung cancer." (PMID 32133284, 2020). "Therefore, it is important to identify target genes and accurately manage lung cancer, and mEGFRs are considered strong biomarkers for predicting the response to an EGFR-TKI." (PMID 32517757, 2020). "Similarly, gefitinib (Iressa), an EGFR small molecule inhibitor, attenuated DNA repair in lung cancer cells exposed to ionizing radiation, thereby revealing an ability of EGFR signaling to modulate DDR in cancer cells during an external DNA damage." (PMID 31948066, 2020). "HCC827 is an EGFR exon19del mutant lung cancer cell line sensitive to EGFR inhibition." (PMID 32317663, 2020).
lung cancer (continued). "EGFR/HER2 inhibitors combined with CDK4/6 inhibitors may increase the sensitivity to EGFR inhibitor-resistant lung cancer cells." (PMID 32357912, 2020). "Moreover, the synergistic therapeutic effects of EGFR tyrosine kinase inhibitor and arsenic trioxide led to a reduction in the level of BASP1 protein observed in lung cancer cells with acquired resistance to EGFR inhibitors." (PMID 33042262, 2020). "Here, we hypothesize that defective degradation of activated proliferative and survival signals in EGFR mutant lung cancers contributes to their dependence on the EGFR pathway." (PMID 32194831, 2020). "Moreover, metformin reversed and delayed acquired resistance to EGFR TKIs as well as suppressed cancer stemness in EGFR-mutant lung cancer." (PMID 33014814, 2020). "To test the hypothesis, we used an EGFR-mutant PC9 lung cancer cell line that is highly sensitive to TKIs initially and developed a stable drug-resistant cell line PC9GR after long-term exposure to gefitinib." (PMID 32923394, 2020). "This could further drive the impact FBLN1 downregulation has on EGFR dependent lung cancer cells (NSCLC)." (PMID 32719793, 2020). "Interestingly, elevation of YAP/TAZ was reported to participate in resistance to EGFR-TKI therapies by lung cancer cells." (PMID 33375719, 2020). "A recent study confirms that lung cancer stem cells inversely express EGFR and MIG6 genes." (PMID 32377505, 2020). "Moreover, a combination of silmitasertib and another EGFR inhibitor, gefitinib, decreases proliferation and induces apoptosis in lung cancer cells." (PMID 32626654, 2020). "Thus, our study demonstrates for the first time that ketoconazole treatment inhibits upregulation of mitochondrial cholesterol and thereby overcomes EGFR‐TKI resistance in lung cancer cells." (PMID 32123859, 2020). "Activating EGFR mutations are found in 10–30% of lung adenocarcinomas and are the major cause of lung cancer in never smokers." (PMID 32897190, 2020). "A large number of successfully retargeted AdVs towards neuronal cells, brain endothelial cells, vascular endothelial cells, prostate cancer, lung cancer, pancreatic cancer, muscle cells, and receptors-like epidermal growth factor receptor (EGFR) have been reported." (PMID 32526919, 2020). "In non-smokers, epidermal growth factor receptor (EGFR) kinase domain mutations which have been established as valid predictors of increased sensitivity to EGFR kinase inhibitors are prevalent in lung cancers." (PMID 32410828, 2020). "The results indicated that induced-autophagy was related with EGFR-TKI resistance in lung cancer." (PMID 32913468, 2020). "In conclusion, the bone metastasis of EGFR-mutant lung carcinoma has lower FDG uptake compared with EGFR wild-type, and SUVmax could be a valuable noninvasive predictor for EGFR mutations." (PMID 32742498, 2020). "But pulmonary myoepithelial carcinoma is a rare subtype of lung carcinoma; there is no previous report of myoepithelial carcinoma patient harboring EGFR mutation." (PMID 32505185, 2020). "EGFR inhibitors have been extensively used to treat various tumors, in particular lung carcinoma." (PMID 33574751, 2020). "Since it remains questionable that whether EGFR plays an essential role in the Ibr‐7 anti‐tumor effect in lung cancer cells, we knocked down the expression of EGFR by siRNA transfection in A549 cells, and determined the cell proliferation rate by CCK‐8 assay." (PMID 30663221, 2019). "A previous report proposed that an evolutionarily conserved network that regulates EGFR-induced miR-7 expression may target ERF to modulate cell growth in human lung cancer." (PMID 30988068, 2019).
lung cancer (continued). "Further subgroup analysis of EGFR mutation status in patients with/without FH of all cancers or other non-lung cancers did not demonstrate any remarkable difference between subgroups tested (Data not shown)." (PMID 31703574, 2019). "The addition of SCD1 inhibitor could converse these effects via inhibiting SCD1-dependent phosphorylation of EGFR/PI3K/Akt signaling in lung cancer." (PMID 31019378, 2019). "Overall, the previous reviewed data, show that RKIP is an important modulator of relevant intracellular signaling pathways (including MAPK, which is controlled by EGFR), is both a driver and predictor of therapy response in lung cancer, and has an important role in normal lung homeostasis." (PMID 31083461, 2019). "Although the two surveys do show a year-on-year improvement, some patients with advanced lung cancer carrying activating EGFR mutations appear to receive care that is not in line with current evidence and guidelines." (PMID 30811306, 2019). "It has been reported that activation of the oncogenic EGFR pathway enhances the susceptibility of lung cancers to PD-1 blockade in mouse models, suggesting that combination of PD1 blockade with EGFR TKIs may be a promising therapeutic strategy." (PMID 31871778, 2019). "Lung cancer’s endogenous tumour defence largely happens due to different reasons such as the altering residues at drug binding sites, ALK and ROS1 rearrangements, and mutations in N-RAS, K-RAS, B-RAF, EGFR and RET." (PMID 31739412, 2019). "Patients with EGFR-positive lung cancer commonly begin oral treatment as outpatients." (PMID 30653558, 2019). "We hypothesize that administration of Arecoline contributes to lung cancer cell migration through the EGFR/c-Src/FAK pathway via mAChR3 transactivation." (PMID 30925742, 2019). "EGFR gene mutations, which lead to the insensitivity of EGFR-tyrosine kinase inhibitors (EGFR-TKI) are prevalent in never-smoker with lung cancers." (PMID 31139230, 2019). "This may mark the beginning of a new era in overcoming resistance to EGFR-TKIs and suggests a new treatment strategy for lung cancer." (PMID 30609749, 2019). "In addition, one recent study reported that Akt activation is related to EGFR drug resistance in lung cancer." (PMID 30935067, 2019). "In particular, the expression of the HER3 ligand heregulin that we observed in our DMPM series may be able to induce resistance to EGFR-inhibitors, as has been observed in lung cancer." (PMID 31752449, 2019). "In the first human trial of a TargomiR drug, MesomiR-1, the miRNA mimic was the reported tumor suppressing transcript miR-16 and the targeting moiety was an antibody to the epidermal growth factor receptor (EGFR) that is consistently deregulated in lung cancer cells." (PMID 31156715, 2019). "For example, STAT3 is frequently activated and plays oncogenic roles in non-small cell lung adenocarcinomas with the context of EGFR driver mutations, whereas low STAT3 level correlate with increased malignant progression and poor prognosis in lung cancer patients with KRAS mutations." (PMID 31296870, 2019). "Therefore, the identification of new therapeutic methods or agents for the treatment of EGFR-TKI resistant lung cancer is imperative." (PMID 31747941, 2019). "Furthermore, IL-8 plays a central role in the promotion and induction of lung cancer cell proliferation, which is achieved through EGFR transactivation and increased MAPK pathway signaling." (PMID 32039025, 2019). "Notably, overexpression of EGFR in lung cancer and mesothelioma promotes cell growth, invasion and angiogenesis." (PMID 31632972, 2019). "The hypothesis is that Arecoline stimulates A549 lung cancer cell migration by mAChR3 transactivating EGFR and the following c-Src/FAK signaling pathway." (PMID 30925742, 2019).